IDO1 (indoleamine 2,3-dioxygenase 1)
Diseases named in the same sentence as IDO1 in open-access papers (continued):
Sharing a sentence is not in itself a finding about the gene and the disease.
Allergy (18 papers, 2014 to 2025). An allergy is an immune response or reaction to substances that are usually not harmful. "ICOS and IDO1 are proteins related to immunotherapy; relevant target drugs have been produced, and several studies support that they were associated with allergic diseases." (PMID 36077704, 2022). "Notably, the biological mechanism of tryptophan has been linked to allergy through its involvement in the degradation process of the immune-regulatory enzyme indoleamine 2,3-dioxygenase (IDO-1), a process mediated by IFN-γ." (PMID 39683566, 2024). "In fact, the metabolism of tryptophan has been related to allergy through its degradation via the immune-regulatory enzyme indoleamine 2,3-dioxygenase-1 (IDO-1), which is activated by the IFN-γ." (PMID 32024101, 2020). "IDO1 has emerged as a new significant therapeutic target due to its indispensable immunomodulatory roles in pregnancy, cancer, allergy and central nervous system disorders such as Alzheimer’s disease (AD)." (PMID 30777103, 2019). "In their capacity to induce Tregs and inhibit Th17, IDO1-expressing DCs and epithelial cells and kynurenines revealed an unexpected potential in the control of inflammation, allergy, and Th17-driven inflammation in these infections." (PMID 25360137, 2014). "In addition, IDO1, as an immunosuppressive tolerogenic enzyme, has been reported as biomarkers of immune system activation and childhood allergic diseases." (PMID 36077704, 2022). "As a result of their ability to induce differentiation of Treg cells and inhibit Th17 cells, IDO1 is critical to cell lineage commitment in experimental fungal infections and contributes to the overall outcome of inflammation, allergy, and Th17-driven inflammation in these infections." (PMID 25360137, 2014). "Our observation of a significantly lower expression of IDO1 in the responder group at baseline is consistent with conflicting reports of the role of indoleamine 2,3 dioxygenase (IDO) in allergy." (PMID 31690037, 2019). "IDO may also have equivocal roles in allergic diseases, as Th2-mediated allergic airway inflammation in mice was attenuated by treating mice with TLR9 ligands (CpGs) to induce IDO and by ablating IDO1 genes." (PMID 29163470, 2017).
liver cancer (18 papers, 2016 to 2025). An epithelial or non-epithelial malignant neoplasm that arises from the liver. "In liver cancer cell models, inhibiting IDO1 expression can significantly enhance the immune response against the tumor and slow tumor growth." (PMID 39940736, 2025). "IDO1 was elevated in 50% of liver cancer samples while IDO2, TDO2, and AFMID were predominantly downregulated." (PMID 38769298, 2024). "In a mouse liver cancer model, exogenous H2S inhibited IDO1 expression by blocking the STAT3 and NF-κB pathways and reduced IDO1 activity through the H2S/NO crosstalk, effectively stopping tumor progression in mice." (PMID 36588686, 2022). "To investigate the role of Trp metabolic enzymes, we examined the expression of IDO1 and TDO2 in tumor tissues from liver cancer patients." (PMID 34657635, 2021). "In liver cancer treated with Newcastle disease virus (NDV), DCA significantly reduced the release of lactate in cancer cells, activation of signal transducer and activator of transcription 3 (STAT3), up-regulation of indoleamine 2,3-dioxygenase 1 (IDO1), and infiltration of MDSCs." (PMID 33027968, 2020).
lung adenocarcinoma (18 papers, 2014 to 2025). A carcinoma that arises from the lung and is characterized by the presence of malignant glandular epithelial cells. "Here, we show that IL-1β-stimulated lung adenocarcinoma cells with various driver mutations respond with an NFκB-mediated upregulation of IDO1." (PMID 37985999, 2023). "However, to our knowledge, expression of IDO1 in various clinical stages of lung adenocarcinoma and its association with tumor-infiltrating T lymphocyte subsets has not been reported." (PMID 35187162, 2022). "In lung adenocarcinoma patients, IDO1 protein was predominantly localized to the cytoplasm and cell membrane of tumor cells, with higher expression observed in tumor cells closer to normal lung tissue." (PMID 39989741, 2025). "As far as we know, this study is the first to investigate the prognostic value of IDO1 in lung adenocarcinoma brain metastases." (PMID 38267913, 2024). "IDO1 and PD-L1 expression in lung adenocarcinoma cell lines in the presence of IFN-γ and transforming growth factor-β were previously reported to be significantly linked with shorter DSS and OS." (PMID 38539263, 2024). "The result showed patients with high B7-H4 and IDO1 expression in brain metastases had a shorter survival time (log-rank test), and B7-H4 was an independent prognostic factor in lung adenocarcinoma brain metastases patients." (PMID 38267913, 2024). "Analysis of lung adenocarcinoma patient data set from TCGA revealed that IDO1 expression was positively correlated with CD274 and PDCD1LG2 expression." (PMID 37985999, 2023). "Upon IL-1β stimulation, lung adenocarcinoma cells exhibited significant increases in IDO1 mRNA and protein levels, a response that depended on the NFκB pathway." (PMID 37985999, 2023). "We were intrigued to see that the PD-1 ligands PD-L1(CD274 gene) and PD-L2 (PDCD1LG2 gene) mRNA were among top significant genes that were positively correlated with IDO1 mRNA in lung adenocarcinoma tumors." (PMID 37985999, 2023). "In accordance with our results showing that 1-MT induced G2/M arrest, the administration of anti-IDO1 shRNA increased tumor cells in the G2/M phase in a human lung adenocarcinoma cell line." (PMID 36653774, 2023). "Our study has identified IL-1β as an upstream regulator of IDO1/PD-L1 axis of immune suppression in lung adenocarcinoma cells, which is partly through NFκB-p65 activity." (PMID 37985999, 2023). "IDO1 expression is elevated in lung adenocarcinomas relative to the normal adjacent tissue and correlates with advanced clinical stage and lymph node metastasis." (PMID 37985999, 2023). "Here, we provide novel insights on a mechanism that plausibly underlies this effect: namely the induction of immune checkpoint protein IDO1 by IL-1β in lung adenocarcinoma cells." (PMID 37985999, 2023). "The current study demonstrated that the higher level of IDO1 expression in the lung adenocarcinoma was, the less infiltration of T lymphocytes was found in the tumors." (PMID 35187162, 2022). "It was found that the later clinical stage of lung adenocarcinoma was, the higher expression of IDO1 in the tumor but the less infiltration of T lymphocytes was found in the lung adenocarcinomas." (PMID 35187162, 2022). "In the current study, therefore, level of IDO1 expression and number of tumor-infiltrating T cell subsets were assessed in the lung adenocarcinoma and its adjacent normal tissues." (PMID 35187162, 2022). "IDO1 protein and mRNA were detected in various stages of lung adenocarcinoma with highest expression at stage III." (PMID 35187162, 2022). "In NSCLC lung adenocarcinoma patient cohort (from TCGA) Ido-1 gene expression was significantly higher in samples classified as mesenchymal according EMT score." (PMID 36419183, 2022). "Taken together, expression of IDO1 and tumor infiltration of T cell subsets in various clinical stages of lung adenocarcinomas as well as adjacent normal lung tissues were investigated in this study." (PMID 35187162, 2022).
lung adenocarcinoma (continued). "Third, we expected IDO1 expression was further increased while the number of T cells was further reduced in stage IV lung adenocarcinoma tissues." (PMID 35187162, 2022). "IDO1 protein and mRNA were assessed by immunohistochemistry, immunoblotting, and PCR in the 68 resected lung adenocarcinomas at stages I–III as well as adjacent normal lung tissues." (PMID 35187162, 2022). "Evaluation on the IDO1 level by immunohistochemical staining showed that heterogeneity existed in the lung adenocarcinomas." (PMID 35187162, 2022). "We sought to identify peripheral blood markers associated with two immune-related factors—programmed cell death-ligand-2 (PD-L2) and indoleamine 2,3-dioxygenase-1 (IDO1)—that are expressed on tumor cells in primary lung adenocarcinoma (AD) specimens." (PMID 31163080, 2019). "In addition, coexpression of IDO1 and PD-L1 in lung adenocarcinoma was found to indicate a progressive state of the tumor." (PMID 38254043, 2024). "In addition, we also explored the factors related to the prognosis of patients with lung adenocarcinoma brain metastases, and the results revealed the age, expression of B7-H4 and IDO1, and infiltration of CD68+ TAM were related to the prognosis." (PMID 38267913, 2024). "We next tested whether inhibiting IDO1 activity could suppress spheroid growth of lung adenocarcinoma cells." (PMID 37985999, 2023). "To account for complexity of cell-to-cell contacts and formation of a hypoxic core formed under 3D growth conditions, we tested whether IL-1β–mediated induction of IDO1 in lung adenocarcinoma cells was conserved in a spheroid model of cell culture." (PMID 37985999, 2023). "Importantly, IDO1 induction was observed across a spectrum of lung adenocarcinoma cells lines derived from tumors with varying oncogenic activation." (PMID 37985999, 2023). "Our data indicate that regardless of the driver mutations, lung adenocarcinoma cells induce immunosuppressive IDO1 mRNA and protein, but not TDO2, in response to IL-1β stimulation." (PMID 37985999, 2023). "We found that the later stage of lung adenocarcinoma was the higher level of IDO1 was expressed, suggesting IDO1 may play an important role in the progress of lung adenocarcinoma." (PMID 35187162, 2022). "Findings of this study indicated that IDO1 may contribute to the reduction of T lymphocyte infiltration into the lung adenocarcinoma." (PMID 35187162, 2022). "In conclusion, peripheral blood markers could be potential biomarkers to predict the expression of IDO1 in lung adenocarcinoma." (PMID 31163080, 2019). "Moreover, our recent reports indicated that not only PD-L1 but also programmed cell death-ligand-2 (PD-L2), another PD-1 ligand, and IDO1 independently contribute to poor prognoses in patients with resected lung adenocarcinoma (AD)." (PMID 31163080, 2019). "In addition, IDO1 expression in lung adenocarcinoma was found to indicate tumor progression." (PMID 38254043, 2024). "In contrast, high expression of IDO1 was detected in majority (93.33%, 14/15) of stage III lung adenocarcinomas, with only 6.7% (1/15) of stage III tumor tissues showed low expression of IDO1 (P < 0.01)." (PMID 35187162, 2022). "It was found that IDO1 was significantly upregulated in stage I, II, and III lung adenocarcinomas compared to that of adjacent normal lung tissues." (PMID 35187162, 2022). "In this study, protein level and mRNA expression of IDO1 in the resected stage I, II, and III lung adenocarcinomas as well as adjacent normal lung tissues were assessed." (PMID 35187162, 2022). "In a patient cohort of 204 lung adenocarcinoma patients, STAT3 and CYP1B1 expression correlated with IDO1 expression." (PMID 24657910, 2014). "IDO1 was not detectable in the adjacent normal lung tissues, was barely detectable in stage I lung adenocarcinomas, easily detectable in stage II tumor tissues, and most highly expressed in stage III tumor tissues." (PMID 35187162, 2022).
lung adenocarcinoma (continued). "The lack of an inverse correlation between SOCS3 and IDO1 was confirmed using expression data of 215 human mature aggressive B-cell lymphomas and 204 lung adenocarcinomas." (PMID 24657910, 2014). "To determine whether IL-1β regulates IDO1, TDO2, PD-L1, and PD-L2, we measured mRNA and protein levels in lung adenocarcinoma cells lines (A549, H1792, H1838, H2347, H2228, HCC364 and HCC827) grown in 2D or 3D and in immortalized normal lung epithelial cells (HBEC3-KT and HSAEC1-KT)." (PMID 37985999, 2023). "Therefore, the current study was designed to assess the expression of IDO1 and biomarkers of T cell subsets (CD3, CD4, and CD8) in the lung adenocarcinomas as well as adjacent normal lung tissues, which were resected from the patients at stage I, II, and III lung adenocarcinoma." (PMID 35187162, 2022). "This phenomenon may explain why the high expression of IDO1 alone is not significantly related to the prognosis of patients with lung adenocarcinoma." (PMID 33552086, 2020).
multiple sclerosis (18 papers, 2013 to 2026). A progressive autoimmune disorder affecting the central nervous system resulting in demyelination. "Another interesting point is that if IDO-1 deregulation in macrophage/microglia correlated with brain autoimmunity diseases caused by the abnormal entrance of T cells to parenchyma, such as Multiple Sclerosis." (PMID 34735466, 2021). "A PAM of mGlu4 has been demonstrated to activate noncanonical mGluR4 signaling in dendritic cells (DC) and induce a tolerogenic functional phenotype through IDO1, an immunoregulator and reduce neuroinflammation in a murine model of multiple sclerosis." (PMID 33390996, 2020). "Thus, for instance, dendritic cells expressing IDO1, and exosomes derived from dendritic cells overexpressing IDO1 have been shown to display immunosuppressive and anti-inflammatory effects in collagen-induced arthritis and in models of multiple sclerosis." (PMID 37081894, 2023). "In the brain, IDO1 can be induced in microglia by interferon-gamma-producing T helper 1 (Th1) cells, thereby initiating a negative feedback loop, which can down-modulate neuro-inflammation in experimental autoimmune encephalomyelitis (EAE), the animal model of multiple sclerosis (MS)." (PMID 26378585, 2015).
rheumatoid arthritis (18 papers, 2010 to 2026). A chronic, systemic autoimmune disorder characterized by inflammation in the synovial membranes and articular surfaces. "Increased expression of both Ido1 and Gal-9 are associated with MS, Grave’s disease, Hashimoto’s disease, and rheumatoid arthritis." (PMID 27799931, 2016). "The three rate-limiting enzymes of the Trp-Kyn pathway are IDO1, IDO2, and TDO2, with IDO1 promoting inflammation in rheumatoid arthritis (RA)." (PMID 38724970, 2024). "However, investigations have also demonstrated that IDO1 deficiency/inhibition reduced inflammation and metaplasia in chronic gastric inflammation, the development of allergic airway disease, and ameliorated rheumatoid arthritis symptoms via a diminished autoreactive B cell response." (PMID 33925729, 2021).
head and neck squamous cell carcinoma (17 papers, 2016 to 2025). A squamous cell carcinoma that arises from any of the following anatomic sites: lip and oral cavity, nasal cavity, paranasal sinuses, pharynx, larynx, and salivary glands. "Consistent with persister enrichment in ICB treated tumors, ATF3 and IDO1 are induced in 4MOSC159 orthotopic syngeneic mouse head and neck squamous cell carcinoma tumors which have regressed during anti-PD-1 treatment." (PMID 40166148, 2025). "For example, DNA methylation of IDO1 in head and neck squamous cell carcinomas (HNSC) correlates with HPV status and survival." (PMID 35794182, 2022). "In head and neck squamous cell carcinomas (HNSCCs), IDO1 inversely correlates with programmed cell death protein ligand 1, which constitutes an important prognostic biomarker for immune-checkpoint inhibition." (PMID 32117235, 2020). "STAT3 also favors immunosuppressive functions of MDSCs by inducing the expression and the activity of IDO (Indoleamine 2,3-dioxygenase 1) in breast and liver cancers or arginase-1 in head and neck squamous cell carcinoma." (PMID 31480382, 2019). "The probable effect of immunotherapy on head and neck squamous cell carcinomas (HNSCC) patients was determined using an in vitro 3D microfluidic chip, which loaded different ICIs, Indoleamine 2, 3-dioxygenase 1 (IDO1) inhibitors, and PD-L1 antibodies." (PMID 36159996, 2022). "Our data revealed a strong positive correlation between the expression of CCR5, GZMA, IDO1, and PRF1 and CNV in both lung squamous cell carcinoma (LUSC) and head and neck squamous cell carcinoma (HNSC)." (PMID 37646041, 2023).
metastatic disease (17 papers, 2009 to 2025). "In vivo modeling will also determine if dual TDO2/IDO1 inhibition influences primary tumor growth or whether its utility as an adjuvant therapy will reduce the risk of recurrence as a metastatic disease." (PMID 39311710, 2024). "Collectively, our findings demonstrate that dual TDO2/IDO1 inhibition is a promising therapeutic avenue for the blockade of TRP catabolism to reduce TNBC progression to metastatic disease." (PMID 39311710, 2024). "Indoleamine 2,3-dioxygenase 1 (IDO1) is a tryptophan catabolic arthritase that is abundantly expressed in various metastatic tumors." (PMID 39329710, 2024). "Indoleamine 2,3-dioxygenase 1 (IDO1) is another suppressive protein, which is also minimally expressed as PD-1 and only in metastatic disease." (PMID 32878021, 2020). "Because amino acid (AA)-catabolizing enzymes have been shown to regulate immunosuppressive effects, this review investigated the immunosuppressive roles of indoleamine 2,3-dioxygenase 1 (IDO1), a tryptophan (Trp)-catabolizing enzyme, which is overexpressed in various metastatic tumors." (PMID 39371092, 2024). "Increased levels of IDO1 in patient with metastatic disease compared with patients with primary tumors would lead to a strong reduction in L-tryptohpan and a corresponding increase in fatty acid metabolism products (C2 and medium-chain acylcarnitines), as we observed in our cohort." (PMID 31842810, 2019). "In previous studies, high IDO1 expression in CRC was significantly correlated with a reduction in CD3-positive TILs and the presence of metastatic disease, revealing the important role of IDO1 in the therapeutic blockade for this disease." (PMID 36983678, 2023). "In metastatic tumors, age was significantly correlated with OX40 (r=0.46, p=0.025) and inversely correlated with IDO1 (r=-0.41, p=0.045)." (PMID 36313661, 2022). "In the 272 pan-cancer patients who never received immunotherapy, overall survival (OS) from time of advanced/metastatic disease was not correlated with IDO1 level." (PMID 38632994, 2024). "IDO1 expression level was not a prognostic factor for survival from the time of advanced/metastatic disease in immunotherapy-naive patients, nor did IDO1 expression level predict outcome after ICI therapy in the second-line setting or beyond." (PMID 38632994, 2024). "A phase I clinical trial (NCT 02048709) was conducted to assess the curative effect and irAEs of the IDO-1 inhibitor navoximod in recurrent advanced solid tumors, but it failed to prove its effect in metastatic tumors, and thus, further investigation is warranted." (PMID 34367975, 2021).